RAB33B (RAB33B, member RAS oncogene family)
Description:
The small GTPases Rab are key regulators of intracellular membrane trafficking, from the formation of transport vesicles to their fusion with membranes. Rabs cycle between an inactive GDP-bound form and an active GTP-bound form that is able to recruit to membranes different sets of downstream effectors directly responsible for vesicle formation, movement, tethering and fusion. RAB33B acts, in coordination with RAB6A, to regulate intra-Golgi retrograde trafficking. Participates in autophagosome formation by recruiting the ATG12-ATG5-ATG16L1 complex to phagophores, probably in a nucleotide-independent manner.
Synonyms: DKFZP434G099
Tractability: Small molecule: a structure with a bound ligand is known. PROTAC: ubiquitination databases record sites on it; its protein half-life has been measured.
Gene: Protein-coding gene on chromosome 4 (139,453,232 to 139,476,609, forward strand). Ensembl gene ENSG00000172007.
Subcellular location: Golgi apparatus membrane; Golgi apparatus, cis-Golgi network; Preautophagosomal structure membrane
Pathways (Reactome):
Vesicle-mediated transport: Intra-Golgi traffic; TBC/RABGAPs
Metabolism of proteins: RAB geranylgeranylation
Gene Ontology:
Molecular function: G protein activity; GTPase activity; protein binding; GTP binding
Biological process: intra-Golgi vesicle-mediated transport; negative regulation of constitutive secretory pathway; protein localization to Golgi apparatus; protein localization to phagophore assembly site; regulation of cell growth; regulation of epithelial cell proliferation; regulation of Golgi organization; regulation of retrograde vesicle-mediated transport, Golgi to ER; skeletal system morphogenesis; autophagosome assembly; regulation of exocytosis; Rab protein signal transduction
Cellular component: Golgi apparatus; Golgi lumen; Golgi membrane; phagophore assembly site membrane; presynapse
Genetic constraint (gnomAD): Loss-of-function variants: 6 observed, 15.3 expected, observed/expected ratio (o/e) 0.39, 90% interval 0.21 to 0.77. The upper end of that interval is the gene's LOEUF score, 0.77, which puts it in group 3 of 6, group 1 being the genes least tolerant of losing a copy. Missense variants: 257 observed, 313.7 expected, observed/expected ratio (o/e) 0.82, 90% interval 0.74 to 0.91. Synonymous variants: 117 observed, 116.57 expected, observed/expected ratio (o/e) 1, 90% interval 0.86 to 1.17.
Homologues: Orthologues: chimpanzee RAB33B (99% identical), macaque RAB33B (99% identical), pig RAB33B (98% identical), dog RAB33B (97% identical), rat Rab33b (96% identical), mouse Rab33b (95% identical), guinea pig RAB33B (88% identical), tropical clawed frog rab33b (79% identical), zebrafish rab33ba (74% identical). Paralogues in human: RAB33A (58% identical), RAB39A (37% identical), RAB35 (37% identical), RAB39B (35% identical), RAB1B (34% identical), RAB30 (34% identical), RAB1A (34% identical), RAB26 (34% identical), RAB10 (34% identical), RAB12 (33% identical), RAB13 (33% identical), RAB19 (33% identical), and 56 more.
Diseases named in the same sentence as RAB33B in open-access papers:
RAB33B is named in the same sentence as 24 diseases in open-access papers, as found by Europe PMC text mining. Sharing a sentence is not in itself a finding about the gene and the disease. The quoted sentences say what the papers report.
lung carcinoma (5 papers, 2021 to 2025). "Intriguingly, analysis of The Cancer Genome Atlas (TCGA) dataset shows that Rab33b expression is downregulated in lung cancer compared to normal tissues." (PMID 35521520, 2022). "In addition, RAB33B was identified as a biomarker for lung cancer diagnosis." (PMID 34335109, 2021). "Zhang’s group selected a panel of five urinary molecules (ferritin light chain, mitogen-Activated Protein Kinase 1 Interacting Protein 1-Like, fibrinogen Beta Chain, two Member RAS Oncogene Family, RAB33B and RAB15) as a predictive model to differentiate lung cancer from healthy lung tissue." (PMID 33923502, 2021).
Smith-McCort dysplasia (3 papers, 2013 to 2023). "Other Rab proteins of the Golgi complex are also implicated in disease; mutations in RAB33B have recently been shown to lead to Golgi swelling and fragmentation in Smith-McCort dysplasia." (PMID 24025425, 2013). "The identification of specific cargos and/or glycosylation protein targets in both osteoclasts and osteoblasts will be important to further improve our understanding of RAB33B and Smith-McCort dysplasia." (PMID 37359363, 2023). "The gene RAB33B, which encodes a small GTP-binding protein of the RAB family and is associated with Smith-McCort Dysplasia, can illustrate paralog-based functional complementation." (PMID 28542158, 2017). "Interestingly in Dyggve-Melchior-Clausen disease no changes were detected at the level of the Golgi complex, whereas in Smith-McCort Dysplasia reduced RAB33B protein expression levels were correlated with a swollen and fragmented Golgi complex." (PMID 24025425, 2013).
osteosarcoma (2 papers, 2021 to 2022). A usually aggressive malignant bone-forming mesenchymal neoplasm, predominantly affecting adolescents and young adults. "Similar to the U2OS osteosarcoma cell line, retinal pigment epithelial-1 (RPE-1) cells silenced with either Rab33b siRNA_1 or Rab33b siRNA_2 also showed a tendency to increase cell migration." (PMID 35521520, 2022).
Cerebral ischemia (1 paper, 2010). Restriction of arterial blood supply to the brain associated with insufficient oxygenation to support the metabolic requirements of the tissue. "Further studies are needed to clarify the involvement of Rab33B to autophagy after cerebral ischemia, especially later phase than the present study." (PMID 21092243, 2010). "Further studies are needed to clarify the function of Rab33B in cerebral ischemia." (PMID 21092243, 2010).
depression (1 paper, 2022). "In particular, we discovered for the first time that RAB1A, GNAI3, RAB33B, LAMP2, and KIF5B might be potential markers for the diagnosis of depression." (PMID 35559009, 2022).
Dyggve-Melchior-Clausen disease (1 paper, 2013). Dyggve-Melchior-Clausen disease (DMC) is a rare skeletal disorder belonging to the group of spondyloepimetaphyseal dysplasias. "Another observation is that the mutation found in Dyggve-Melchior-Clausen disease occurs at a lysine residue that is conserved in RAB33B orthologs across all species." (PMID 24025425, 2013).
hepatoma (1 paper, 2017). "Using RNA interference (RNAi), we demonstrate that the Golgi/autophagosome-associated Rab33B is required for hepatitis B virus (HBV) propagation in hepatoma cell lines." (PMID 28635671, 2017). "Upon in vitro replication in permissive hepatoma cells, the inactivation of Rab33B led to a decline in the levels of extracelluar virions and intracellular NC, likely as a consequence of defects in intracellular virus traffic events." (PMID 28635671, 2017).
ischemic stroke (1 paper, 2010). A stroke disorder caused by obstruction of blood flow to the brain, due to thrombotic (local blood clot formation) or embolic (due to a blood clot or other material traveling from another site) event. "Thus, control of the Rab33B gene and/or protein after ischemia may prove to be a useful strategy for therapeutic treatment of ischemic stroke." (PMID 21092243, 2010).
osteochondrodysplasia (1 paper, 2023). A term referring to disorders characterized by abnormalities in the development of bones and cartilage. "Smith McCort (SMC) dysplasia is a rare, autosomal recessive, osteochondrodysplasia that can be caused by pathogenic variants in either RAB33B or DYM genes." (PMID 37359363, 2023).
virus infections (1 paper, 2017). "The elucidation of the precise role of Rab33B, possibly in cooperation with the autophagy network, in virus infections will be an important step next forward." (PMID 28635671, 2017).
infection (5 papers, 2017 to 2025). The state of being infected such as from the introduction of a foreign agent such as serum, vaccine, antigenic substance or organism. "Of note, these mutations affect neither the expression nor the translocation of SidJ into infected cells at 6 h post infection, indicating that the persistence of Ub-Rab33b in cells infected with these strains was due to the loss of enzymatic activity." (PMID 28497808, 2017). "Infection with WT Legionella strain (Lp02) showed maximum PR ubiquitination of Rab33b at 2 h post-infection and subsequent reduction, while a strain lacking DupA (ΔdupA) maintained the PR ubiquitination up to 6 h post-infection." (PMID 31732457, 2020). "Yet, in infections with wild-type bacteria, the modification of Rab33b was more extensive in early stages, which argues against the inhibition of SidEs activity by SidJ." (PMID 28497808, 2017). "Furthermore, to explore the relationship between CIV M2 and RAB33B gene expression in more detail, we performed gradient dose transfection and detected the time-different durations of infection in HEK293T." (PMID 40598642, 2025). "Recent studies demonstrated that Rab33B is phosphoribosyl-ubiquitinated by the L. pneumophila SidE family of effector proteins, but its significance in infection as well as the major site of phosphoribosyl-ubiquitination in Rab33B remains unknown." (PMID 33760868, 2021). "The efficient recruitment of Sec22b-containing ERDVs to the LCV was observed at 1 h post infection in Rab6A- and Rab33B-silenced cells, similar to mock-treated cells, implying that loss of both Rab proteins does not affect the uptake of L. pneumophila or the remodeling of the LCV." (PMID 33760868, 2021). "Both endogenous and mRFP-tagged Rab6A and Rab33B were detected in a significant fraction of LCVs, and the recruitment of these Rabs to the LCVs are increasing at 2 h post infection, corresponding to the time when ER protein calnexin starts to accumulate on the LCV." (PMID 33760868, 2021). "Moreover, deletion of DupB (ΔdupB) or both DupA and DupB (ΔdupA/B) led to an increased and more prolonged endogenous Rab33b PR ubiquitination 4–6 h post-infection." (PMID 31732457, 2020). "However, complementation with a plasmid expressing wild-type SidJ, but not with a plasmid expressing the D542A SidJ mutant, reduced Rab33b PR-ubiquitination to a level comparable to that seen during infection with the wild-type Legionella strain." (PMID 31682223, 2019). "The results showed that RAB33B gene expression was positively regulated by CIV M2 overexpression in both a dose-dependent manner and in response to infection duration." (PMID 40598642, 2025). "Conversely, RAB33B silencing inhibited CIV replication, especially early in infection." (PMID 40598642, 2025). "Silencing of Rab6A did not significantly affect Rab33B recruitment to the LCV at 4 h post infection (top row)." (PMID 33760868, 2021). "Intriguingly, in cells infected with bacterial strains lacking SidJ activity, the levels of Ub-Rab33b also declined as the infection proceeded, especially at 6 h postinfection (strains 3 and 5)." (PMID 28497808, 2017). "Consistent with the deubiquitinase activity of SidJ, the amount of Ub-Rab33b in cells infected with a strain lacking sidJ was considerably higher, as was also the case for infections with the mutant complemented with the enzymatically inactive SidJ (strains 3 and 5)." (PMID 28497808, 2017).
cancer (1 paper, 2022). A tumor composed of atypical neoplastic, often pleomorphic cells that invade other tissues. "Rab33b expression also correlates with Exoc6 expression, suggesting a relevance for the Rab33b-Exoc6 axis in cancer." (PMID 35521520, 2022). "Moreover, despite our analysis of The Cancer Genome Atlas (TCGA) datasets indicates a correlation between Rab33b and Exoc6 expression in cancer, the precise role of Rab33b-Exoc6 axis in cancer progression and metastasis has not been investigated and will require future studies." (PMID 35521520, 2022).
genetic disorder (1 paper, 2021). "The c.174delC; p.(Asp60ThrfsTer7) variant identified in this research adds to the allelic spectrum of RAB33B variants of this rare genetic disorder." (PMID 34284742, 2021).
skeletal disease (1 paper, 2019). "One reason for interest in Rab33b specifically, is that its dysfunction has been linked to a rare skeletal disease, Smith–McCort Dysplasia (SMC), therefore highlighting important unsolved questions around the complete functional role of Rab33b." (PMID 31408960, 2019).
tumor (1 paper, 2021). "Taken together, SLC7A11 acted as a ceRNA for STX17, UVRAG, and RAB33B in 20, 12, and 12 different tumor types, respectively, and acted as a ceRNA for the three genes in 379 OC tissues and in 90 drug-resistant tissues." (PMID 34790572, 2021).
RAB33B also shares sentences with these, for which no sentence is quoted: bladder cancer (1 paper); cervical cancer (1); colorectal cancer (1); influenza (1); ischemia (1); Legionella infection (1); melanoma (1); skeletal dysplasia (1); transient cerebral ischemia (1).